NIPSNAP3B (nipsnap homolog 3B)
Synonyms: NIPSNAP3; FLJ11275; SNAP1; FP944
Tractability: PROTAC: its protein half-life has been measured.
Gene: Protein-coding gene on chromosome 9 (104,763,850 to 104,777,764, forward strand). Ensembl gene ENSG00000165028.
Gene Ontology:
Biological process: mitophagy
Cellular component: mitochondrion
Genetic constraint (gnomAD): Loss-of-function variants: 26 observed, 31.47 expected, observed/expected ratio (o/e) 0.83, 90% interval 0.61 to 1.15. The upper end of that interval is the gene's LOEUF score, 1.15, which puts it in group 5 of 6, group 1 being the genes least tolerant of losing a copy. Missense variants: 268 observed, 305.43 expected, observed/expected ratio (o/e) 0.88, 90% interval 0.79 to 0.97. Synonymous variants: 106 observed, 107.57 expected, observed/expected ratio (o/e) 0.99, 90% interval 0.84 to 1.16.
Homologues: Orthologues: chimpanzee NIPSNAP3B (99% identical), mouse Nipsnap3b (78% identical), macaque NIPSNAP3B (77% identical), rat Nipsnap3a (74% identical), rat Nipsnap3a (72% identical), mouse Nipsnap3a (70% identical), tropical clawed frog nipsnap3a (57% identical), zebrafish nipsnap3a (57% identical), Caenorhabditis elegans K02D10.1 (22% identical), Drosophila melanogaster Nipsnap (21% identical). Paralogues in human: NIPSNAP3A (87% identical), NIPSNAP1 (26% identical), NIPSNAP2 (25% identical).
Diseases named in the same sentence as NIPSNAP3B in open-access papers:
NIPSNAP3B is named in the same sentence as 5 diseases in open-access papers, as found by Europe PMC text mining. Sharing a sentence is not in itself a finding about the gene and the disease. The quoted sentences say what the papers report.
anemia (1 paper, 2022). A reduction in the number of red blood cells, the amount of hemoglobin, and/or the volume of packed red blood cells. "NIPSNAP3B protein belongs to a vesicular trafficking-related protein family, and seems to be associated with type I 3-methylglutaconic aciduria and anemia of prematurity." (PMID 36233195, 2022).
NIPSNAP3B also shares sentences with these, for which no sentence is quoted: neuroblastoma (1 paper); sarcopenia (1); type I 3-methylglutaconic aciduria (1); virus infection (1).